Y_RNA (Y RNA )
Gene: Miscellaneous RNA gene on chromosome 17 (47,557,413 to 47,557,514, forward strand). Ensembl gene ENSG00000206734.
Homologues: Orthologues: chimpanzee Y_RNA (98% identical), macaque Y_RNA (95% identical). Paralogues in human: Y_RNA (98% identical), Y_RNA (89% identical), RNY3 (88% identical), Y_RNA (88% identical), Y_RNA (87% identical), RNY3P1 (86% identical), Y_RNA (86% identical), Y_RNA (85% identical), RNY3P9 (84% identical), Y_RNA (84% identical), RNY3P4 (83% identical), Y_RNA (83% identical), and 96 more.